TIGIT (T cell immunoreceptor with Ig and ITIM domains)
Diseases named in the same sentence as TIGIT in open-access papers (continued):
Sharing a sentence is not in itself a finding about the gene and the disease.
Sepsis (continued). "However, in sepsis with an immunologically experienced background, TIGIT blockade in septic mice that had received pathogen exposure showed a deteriorative 7-day survival because of apoptosis of memory T cells and decreased cytokine-producing T cells." (PMID 38545097, 2024). "The TIGIT+ subset of Tregs is particularly important in determining immune outcomes post-sepsis." (PMID 39594987, 2024). "In this study, TIGIT knockout mice (TIGIT-/-) and anti-TIGIT antibody were employed to interrogate whether TIGIT is involved in bacteria clearance at the acute phase of experimental sepsis." (PMID 38545097, 2024). "In this study, TIGIT modulated CD4+ T cell immunity against bacterial infection during sepsis." (PMID 38545097, 2024). "Together, this study highlights that immunomodulatory therapy targeting TIGIT signaling may have potential value at the acute stage of sepsis." (PMID 38545097, 2024). "In addition, tissue injury and bacteria burden in the peritoneal cavity and liver was reduced in TIGIT-/- mice with CLP induced sepsis." (PMID 38545097, 2024). "Given the role of TIGIT in negative regulation of CD4+ T cell function in the context of acute sepsis, we determined whether TIGIT blockade could lead to similarly relieved prognosis shown in TIGIT deficient mice." (PMID 38545097, 2024). "Therefore, we identified TIGIT as a marker of early T cell activation and TIGIT+ T cells possessed a proinflammatory trait at the initiated stage of sepsis." (PMID 38545097, 2024). "TIGIT was upregulated in Treg and NK cells of healthy and cancer sepsis mice." (PMID 38114466, 2023). "Furthermore, the anti-TIGIT antibody reversed sepsis-induced T cell apoptosis in cancer septic mice and increased their 7-day survival in cancer septic mice." (PMID 38114466, 2023). "Expression of TIGIT on T cells was significantly upregulated in sepsis patients, and in vitro blockade of TIGIT using an anti-TIGIT antibody restored the frequency of cytokine-producing T cells in sepsis patients." (PMID 38114466, 2023). "It has also been shown that TIGIT blockade decreased T-cell function during sepsis." (PMID 35844584, 2022). "In addition to its expression and cell-autonomous effect on effector T cells, TIGIT is also expressed on Tregs, where it serves to promote Treg suppressor function during sepsis." (PMID 33682797, 2021). "To determine whether anti-TIGIT impacted cell proliferation in the setting of CA sepsis, we measured the frequency of Ki-67+–proliferating T cells in the spleens of anti-TIGIT–treated CA septic mice versus PBS-treated CA septic mice." (PMID 34100383, 2021). "TIGIT was upregulated on T cells during sepsis in both PH mice and mice with preexisting CA." (PMID 34100383, 2021). "We next interrogated the cellular mechanisms underlying the ability of the anti-TIGIT treatment to protect CA septic mice from death during sepsis but not PH septic mice." (PMID 34100383, 2021). "TIGIT expression is higher on CD8+ T cells in memory versus previously naive mice during sepsis." (PMID 33682797, 2021). "Indeed, additional work in other models of sepsis, and in human septic patients, will be required to fully elucidate the role of TIGIT in sepsis-induced immune dysregulation." (PMID 33682797, 2021). "It is therefore interesting to speculate that anti-TIGIT and anti–PD-1 coblockade might be particularly effective at inhibiting sepsis mortality in animals with preexisting malignancy." (PMID 34100383, 2021). "Treatment of CA septic animals but not PH septic animals with anti-TIGIT mAb significantly reversed sepsis-induced loss of CD4+ T cells, CD8+ T cells, Foxp3+ Treg, and CD19+ B cells in the spleen, which was the result of decreased caspase-3+ apoptotic cells." (PMID 34100383, 2021).
Sepsis (continued). "Thus, the fact that αTIGIT Ab had no impact on the survival in previously naive septic mice, whereas it sharply worsened survival in memory mice with sepsis, has important implications for the role of TIGIT during human immune responses in sepsis." (PMID 33682797, 2021). "The antiapoptotic effect of the TIGIT mAb could be a result of the concurrent downregulation of PD-1 on T cells during sepsis." (PMID 34100383, 2021). "Although TIGIT is not appreciably expressed on B cells, in the current study we found that sepsis-induced B cell loss was also reversed by anti-TIGIT treatment, indicating that the treatment did not function solely in a cell-autonomous manner." (PMID 34100383, 2021). "The mechanism by which anti-TIGIT modulates B cell survival during sepsis remains to be elucidated." (PMID 34100383, 2021). "During late-stage sepsis, TIGIT-expressing Foxp3+ Tregs exhibit enhanced suppressive function dependent on the IL-33/ST2/STAT6/M2 macrophage axis, suggesting that IL-33 or anti-TIGIT therapy may represent a promising strategy for the treatment of immunosuppressive sepsis." (PMID 40806563, 2025). "However, the role of the TIGIT pathway in the observed increased sepsis mortality in animals with preexisting malignancy is unknown." (PMID 34100383, 2021). "Thus, future investigation will be required to determine whether the effects of anti-TIGIT Ab identified in this Lewis lung carcinoma (LLC)/CLP model hold true for other models of sepsis and for other tumor types." (PMID 34100383, 2021). "Given the previous finding that TIGIT expressed on T cells was increased in memory septic mice compared with their previously naive counterparts, we hypothesized that treatment with αTIGIT Ab might confer a survival benefit in memory mice following sepsis." (PMID 33682797, 2021). "Notably, the use of TIGIT antibodies can restore the function of T cells from sepsis patients ex vivo, suggesting that blocking TIGIT may be a new approach for the immunotherapy of sepsis." (PMID 40364841, 2025). "In CLP-induced sepsis, CD4+ T cells from TIGIT-/- mice shown increased proliferation potency and cytokine production when compared with that from WT mice." (PMID 38545097, 2024). "The expression of TIGIT in splenic T cells and NK cells was significantly elevated at 24 hours post CLP.TIGIT and CD155 mRNA levels were upregulated in sepsis-involved organs when mice were challenged with CLP." (PMID 38545097, 2024). "We re-examined the response to ICI treatment in sepsis using PANscore and found that PD-1 was more expressed in the LowPANscore subgroup, while PD-L1, LAG3, TIGIT, TNFRSF9, CD40, IDO1 were expressed in the HighPANscore subgroup (P<0.05)." (PMID 38239341, 2023). "TIGIT was also upregulated on total CD4+ T cells, Foxp3+ Treg, CD4+ Foxp3– Tconv, and NK cells after sepsis in CA mice." (PMID 34100383, 2021). "In PH mice, TIGIT was upregulated on total CD4+ T cells, Foxp3+ Treg, CD4+ Foxp3– T conventional cells (Tconvs), and NK cells on days 2 and 3 after sepsis compared with sham controls." (PMID 34100383, 2021). "During sepsis, IL-33 released by damaged cells initiates a signaling cascade through its receptor ST2 on M2 macrophages that favors the expansion of the highly suppressive TIGIT+FOXP3+T regulatory cells." (PMID 37604833, 2023). "Sepsis survival was significantly (P = 0.0081) improved in anti-TIGIT–treated mice with preexistent malignancy but not in PH mice." (PMID 34100383, 2021). "Results indicated that whereas anti-TIGIT mAb failed to improve sepsis survival in PH septic mice, the survival of CA septic mice was significantly improved by anti-TIGIT." (PMID 34100383, 2021). "Results indicate that anti-TIGIT treatment mitigated lymphocyte depletion and sepsis mortality in cancer (CA) septic mice but not in previously healthy (PH) mice, illuminating a potential therapeutic target for septic patients with preexisting malignancy." (PMID 34100383, 2021).
Sepsis (continued). "In addition, the expression of FOXP3, CTLA4, TIGIT, TNFRSF18, and IL2RA, key functional genes of Tregs, was increased in the E-SEP group, suggesting that the immunosuppressive effect of Tregs was enhanced in the elderly with sepsis." (PMID 38909272, 2024). "However, the kinetics and distribution of TIGIT expression during sepsis is not known." (PMID 34100383, 2021).
cervical cancer (14 papers, 2019 to 2025). A primary or metastatic malignant neoplasm involving the cervix. "Consistent with these mechanistic insights, TIGIT has been linked to poor prognosis in cervical cancer (CC), highlighting its potential role in mediating immune evasion and disease progression in this malignancy." (PMID 40747615, 2025). "Furthermore, in the same study for cervical cancer was observed that the advanced T cell differentiation (CD27–CCR7–CD45RA–) of PD-1+TIGIT+2B4+TIM3+KLRG-1–CTLA4– CD8+ TILs was associated with 60% of poorly differentiated cervical cancer." (PMID 35656508, 2022). "Furthermore, we found that a higher frequency of advanced differentiation stage T cells (CD27–CCR7–CD45RA–) among the “shared” subset (PD-1+Tim-3+TIGIT+2B4+KLRG-1–CTLA-4–) in bulk CD8 TILs was associated with poorly differentiated cancer type in cervical cancer patients." (PMID 31709176, 2019). "In this analysis of known and emerging inhibitory checkpoint receptors in patients with cervical cancer, we observed that in addition to an increase in PD-1 and TIGIT, the emerging receptors Tim-3, LAG-3 and NKG2A were likewise upregulated." (PMID 41300994, 2025). "In contrast to our findings in cervical cancer, AC of the lung often shows higher expression of immune checkpoints such as TIGIT and VISTA, contributing to its immunosuppressive phenotype." (PMID 40639721, 2025). "In summary, the TIGIT/CD155 signalling exhibits enhanced activity in patients with cervical cancer and mouse models and is related to immunosuppression." (PMID 35729552, 2022). "The expression of CD155 and TIGIT in cervical cancer tissues was detected using flow cytometry, immunohistochemistry (IHC) and gene expression profiling." (PMID 35729552, 2022). "Our study showed that TIGIT was upregulated in CD8+ T cells that infiltrated the tumour tissue of patients with cervical cancer." (PMID 35729552, 2022). "In our study, we evaluated the role of TIGIT/CD155 checkpoints in the progression of cervical cancer." (PMID 35729552, 2022). "The ratio of CD8+TIGIT+ cells in cervical cancer patients and HSIL patients was significantly higher than that of normal cervix." (PMID 35729552, 2022). "TIGIT was expressed at significantly higher levels in patients with cervical cancer than normal people." (PMID 35729552, 2022). "TIGIT expression in patients with cervical cancer was significantly higher than that in patients with HSIL and normal cervix." (PMID 35729552, 2022). "The number of CD8+TIGIT+ cells in cervical cancer tissues was significantly higher than that in adjacent cancer tissues." (PMID 35729552, 2022). "CD155, which is expressed in cervical cancer cells, interacts with TIGIT and impairs CD8+ T cell effector function." (PMID 35729552, 2022). "The number of CD8+TIGIT+ cells is significantly increased in patients with cervical cancer, according to our findings." (PMID 35729552, 2022). "High TIGIT expression in CD8+ T lymphocytes from patients with cervical cancer promotes the exhaustion of CD8+ T lymphocytes." (PMID 35729552, 2022). "We further conducted T-cell differentiation analysis of the identified shared subset, PD-1+TIGIT+2B4+Tim-3+KLRG-1–CTLA-4– in bulk CD8 TILs from 10 cervical cancer patients." (PMID 31709176, 2019). "Interestingly, CD155, the ligand for TIGIT, was found to be highly expressed in cervical cancer tissues and negatively correlated with infiltrating CD8+ T cell percentages." (PMID 41300994, 2025). "However, the specific mechanism of action of TIGIT in cervical cancer remains to be further elucidated." (PMID 40165902, 2025). "Besides the widely researched target such as CTLA-4 and PD-1/PD-L1, some novel co-inhibitory immune checkpoints and their antibodies have also been explored in cervical cancer, such as TIGIT, LAG-3, and TIM-3." (PMID 36817443, 2023). "TIGIT expression was elevated in patients with cervical cancer." (PMID 35729552, 2022).
cervical cancer (continued). "Targeting the TIGIT/CD155 signalling pathway may be a potential therapeutic strategy for the treatment of cervical cancer." (PMID 35729552, 2022). "Our research shows that TIGIT/CD155 is a potential therapeutic target for cervical cancer." (PMID 35729552, 2022). "Our research results showed that TIGIT is expected to become a new target for the treatment of cervical cancer, and treatment with its blocking antibody alone or in combination with anti-PD-1/PD-L1 antibodies exerts significant effects in preclinical models of cervical cancer." (PMID 35729552, 2022). "We analysed the differential expression of TIGIT in cervical cancer and normal cervical tissues from TCGA and GEO databases to determine whether TIGIT is involved in cervical cancer progression." (PMID 35729552, 2022). "Conversely, the majority (60%) of PD-1+TIGIT+2B4+Tim-3+KLRG-1–CTLA-4– CD8 TILs from most (4/5) of the moderately differentiated cervical cancer samples displayed an intermediate T-cell differentiation phenotype, and a minor fraction (40%) displayed advanced T-cell differentiation phenotypes." (PMID 31709176, 2019). "Thus, a combination of PD-1 and TIGIT inhibitors might represent a useful treatment for cervical cancer." (PMID 35729552, 2022). "In cervical cancer patients, we found CSCC cohorts obtained higher TMB score, MSI score and common inhibitory checkpoints expression (e.g., PDCD1, CD274, BTLA, CTLA4, TIGIT, etc.), accompanied by more abundant immunocytes infiltration." (PMID 38206304, 2024). "We observed that TIGIT was positively correlated with PD-1, LAG3, Tim3 on CD8+ T cells from PBMC of patients with cervical cancer." (PMID 35729552, 2022). "The role and mechanism of TIGIT/CD155 in cervical cancer have not been studied." (PMID 35729552, 2022). "Therefore, we tested the expression of TIGIT with coinhibitory receptor PD-1, lymphocyte activation gene 3 protein (LAG3), and T cell immunoglobulin and mucin domain-containing protein 3 (Tim3) in the PBMC of cervical cancer." (PMID 35729552, 2022).
bladder cancer (13 papers, 2021 to 2025). "have found that the frequency of TIGIT+ Tregs was significantly increased in patients with bladder cancer by single‐cell sequencing." (PMID 35474948, 2022). "Given the good performance of the monoclonal antibody of TIGIT (α-TIGIT) against some carcinomas, we explored the antitumor capacity of TIGIT antibodies against bladder cancer." (PMID 35069212, 2021). "We also illustrated the mechanism of the dual effect of targeting TIGIT and revealed the metastasis-promoting effect of IL-32 in bladder cancer." (PMID 35069212, 2021). "Collectively, these findings raise the possibility of utilizing TIGIT as a target against bladder cancer from the bench to the bedside." (PMID 35069212, 2021). "Fortunately, targeting TIGIT had a dual effect, not only upregulating the immune response against bladder cancer but also inhibiting its metastasis." (PMID 35069212, 2021). "In this study, using single-cell sequencing technology, we found that Treg cells in bladder cancer tissues highly expressed TIGIT, demonstrating it as a more suitable therapeutic target." (PMID 35069212, 2021). "Conversely, targeting TIGIT with anti-TIGIT antibodies enhanced the antitumor immune capacity of the host against bladder cancer." (PMID 35069212, 2021). "Taken together, our study demonstrated the enrichment of TIGIT+ Treg cells in bladder cancer tissues." (PMID 35069212, 2021). "To establish an animal model to test the function of targeting TIGIT or IL-32 against bladder cancer, we inoculated C57B6/J mice with MBT-2 cells and analyzed the colocalization of IL-32 and Treg cells." (PMID 35069212, 2021). "In this study, we identified a specific subset of Treg cells in human bladder cancer tissues that highly expressed TIGIT and IL-32." (PMID 35069212, 2021). "To verify the protein expression of TIGIT in bladder cancer tissues, we performed immunohistochemistry (IHC) analysis of TIGIT in both bladder cancer and paracancerous tissues in patients and mice." (PMID 35069212, 2021). "In patients with bladder cancer, TIGIT expression has also been predominantly co-expressed on PD-1+ tumor-infiltrating CD8+ T-cells." (PMID 34638729, 2021). "To verify the expression of IL-32 in Treg cells in bladder cancer tissues, we analyzed the abundances of IL-32, TIGIT, FOXP3, and CD25 in the TCGA and GTEx as previously reported." (PMID 35069212, 2021). "As expected, we noticed that IL-32 was also colocalized with FOXP3 and TIGIT in murine bladder cancer tissues." (PMID 35069212, 2021). "The role of TIGIT in cancer progression was updated in bladder cancer." (PMID 35656508, 2022). "Therefore, TIGIT+ T cells have a prognostic role in clinical outcomes in bladder cancer and seem to be a predictive biomarker for inferior adjuvant chemotherapy responsiveness." (PMID 35656508, 2022). "As a result, targeting TIGIT to suppress the metastasis of tumor may be a novel insight for patients with bladder cancer." (PMID 35474948, 2022). "In support of this, the same study found that anti-TIGIT monoclonal antibodies, when used alone, have a dual effect: they boost the antitumor activities of T cells while decreasing IL-32, which in turn inhibits bladder cancer metastasis." (PMID 35656508, 2022). "Overall, our study revealed the existence of TIGIT+ IL-32+ Treg cells in bladder cancer tissues." (PMID 35069212, 2021). "Thus, we have provided novel insights into the function of IL-32 in bladder cancer and the effect of anti-TIGIT monoclonal antibodies against bladder cancer." (PMID 35069212, 2021). "Given the high abundance of IL-32 in Treg cells in bladder cancer tissues, we investigated whether targeting TIGIT with α-TIGIT suppresses the secretion of IL-32." (PMID 35069212, 2021). "Hence, as an immune checkpoint, TIGIT not only enhances the antitumor immune response but also inhibits the metastasis of bladder cancer cells by suppressing the expression of IL-32." (PMID 35069212, 2021).